ADORA2A (adenosine A2a receptor)
Diseases named in the same sentence as ADORA2A in open-access papers (continued):
Sharing a sentence is not in itself a finding about the gene and the disease.
breast carcinoma (21 papers, 2019 to 2025). "Targeting adenosine A2A receptors (A2AR inhibitors) significantly boosted γδT cell cytotoxicity, leading to improved tumor regression in breast cancer models." (PMID 40226616, 2025). "The greatest proportion of high ADORA2A expressors was found in neuroendocrine and breast cancers and sarcomas, whereas the lowest was found in colorectal and ovarian cancers, albeit with patient-to-patient variability." (PMID 38731962, 2024). "On the other hand, it has recently been reported that suppression of adenosine production or ADORA2A activation in renal and mammary carcinomas enhances T cell and natural killer cell function and suppresses MDSCs." (PMID 38099497, 2023). "Conversely, ADORA2A protein shows lower relevance to breast cancer proteins." (PMID 40417221, 2025). "ADORA2A was observed to be highly expressed in luminal breast cancer." (PMID 32602545, 2020). "Furthermore, the integration of network pharmacology and molecular docking analyses revealed key targets associated with the anti-tumor effects of the pericarp, including PTGER3, DRD2, and ADORA2A, which present novel therapeutic targets for breast cancer treatment." (PMID 39682950, 2024).
epilepsy (20 papers, 2014 to 2026). A brain disorder characterized by episodes of abnormally increased neuronal discharge resulting in transient episodes of sensory or motor neurological dysfunction, or psychic dysfunction. "The data from bioinformatics analysis lack experimental validation including in vitro and in vivo studies, which will further be performed to elucidate the underlying mechanisms of ADORA2A on epilepsy." (PMID 33262686, 2020). "ADA and ADK, identified as key target genes of ADORA2A on epilepsy, are involved in glioma progression, and their upregulated expression in peritumoral tissues is associated with epilepsy in glioma patients." (PMID 33262686, 2020). "Four key epilepsy-associated genes for ADORA2A principally belong to “purine nucleoside biosynthetic process,” “leishmania infection,” “negative regulation of neuron death,” and “aging,” most of which are concerned with epileptogenesis." (PMID 33262686, 2020). "Based on the association study, the underlying mechanisms of ADORA2A in epilepsy were further explored by bioinformatics analysis." (PMID 33262686, 2020). "Furthermore, epilepsy studies have shown that alterations of adenosine levels and receptors, including ADORA2A, are linked with neuronal damage and CNS hyperexcitability, leading to abnormal neuronal circuitry and epileptogenesis." (PMID 39258473, 2024). "Fourteen epilepsy-associated genes were identified as potential targets of ADORA2A in epilepsy, and four key genes including NT5E, ENTPD1, ADA, and ADK were mainly involved in the “negative regulation of neuron death” and “purine nucleoside biosynthetic process” biological processes." (PMID 33262686, 2020). "Furthermore, dysregulation in ADORA1/ADORA2A expression was associated with glioma development, and a low level of ADORA1/ADORA2A expression could increase the susceptibility of tumor-associated epilepsy." (PMID 33262686, 2020). "However, the role and the underlying mechanisms of ADORA2A in epilepsy remain unclear and need to be elucidated." (PMID 33262686, 2020). "These suggest that ADORA2A exerted its effects on the genesis of epilepsy and other neurologic disorders possibly through preventing neuron death and regulating purine nucleoside biosynthesis by purinergic signaling." (PMID 33262686, 2020). "After removing the duplicates from two databases, 5,166 genes were finally obtained for epilepsy and then intersected with 20 genes of ADORA2A from the PPI analysis." (PMID 33262686, 2020). "Our ongoing study will further validate the role of ADORA2A in epilepsy and provide insights into the molecular mechanisms of neurologic and developmental comorbidities." (PMID 33262686, 2020). "However, the relationship between epilepsy and SNPs from the purinergic signaling facet, particularly adenosine A2A receptors (A2AR) and 5′-nucleotidase (CD73), currently has only a limited number of investigations." (PMID 37063258, 2023). "Accordingly, the corresponding gene (ADORA2A) is studied as a promising candidate for epilepsy." (PMID 37063258, 2023). "In our study, BDNF was identified as the target gene of ADORA2A on epilepsy by PPI analysis." (PMID 33262686, 2020). "Fourteen ADORA2A target genes related to epilepsy were identified by the protein–protein interaction analysis, which were mainly involved in the biological processes of “negative regulation of neuron death” and “purine nucleoside biosynthetic process” through the gene functional enrichment analysis." (PMID 33262686, 2020). "Genotype frequencies of all investigated ADORA2A and CD73 SNPs conformed to the Hardy–Weinberg equilibrium in epilepsy and the healthy control samples." (PMID 37063258, 2023). "Our ongoing study will increase the sample size and validate the role of ADORA2A, BDNF, and NTRK2 in epilepsy." (PMID 33262686, 2020). "A reduced expression of ADORA2A was observed in the peri-tumor tissue of patients with epilepsy contrary to patients without epilepsy." (PMID 33262686, 2020).
renal cell carcinoma (18 papers, 2018 to 2024). "Adenosine mediates TME immunosuppression of immune cells via ADORA2A, and in addition, drugs targeting ADORA2A have entered phase I clinical trials for immunotherapy of renal cell carcinoma." (PMID 36911389, 2023). "ADORA2A can also serve as a targetable immune checkpoint, and studies have shown that blocking ADORA2A can effectively treat refractory renal cell carcinoma." (PMID 37627013, 2023). "Drugs targeting ADORA2A have entered phase I clinical trials for the immunotherapy of patients with renal cell carcinoma." (PMID 35280985, 2022).
Huntington disease (17 papers, 2010 to 2025). Huntington disease (HD) is a rare neurodegenerative disorder of the central nervous system characterized by unwanted choreatic movements, behavioral and psychiatric disturbances and dementia. "Furthermore, we found that some DORCs, such as CNR1, HOMER1, ADORA2A, and DRD2, have been reported to be downregulated in patients with Huntington's disease in the striatum." (PMID 38091510, 2022).
colitis (16 papers, 2011 to 2025). Inflammation of the colon. "Consistent with its antiinflammatory and immunosuppressive role, the protective effects of adenosine A2A receptor stimulation have been observed in various models of autoimmune disease, such as rheumatoid arthritis, colitis, and hepatitis." (PMID 21486435, 2011).
glioma (16 papers, 2017 to 2025). A benign or malignant brain and spinal cord tumor that arises from glial cells (astrocytes, oligodendrocytes, ependymal cells). "It had been shown that ADORA2A (adenosine A2a receptor) expression was associated with glioma development and it was found to be significantly more immunoreactive in gliomas containing infiltrating tumor cells than in normal brain tissue." (PMID 39039366, 2024). "The previous studies showed that a low level of adenosine A1 receptor/adenosine A2a receptor expression, which was observed in low-grade gliomas, could increase susceptibility to tumor-related epilepsy." (PMID 29212163, 2017). "Furthermore, we found that 5 immune inhibitors (KDR, TIGIT, VTCN1, LAG3 and ADORA2A) and 2 immune stimulators (ICOS and TNFRSF25) were significantly associated with HIC2 in gliomas." (PMID 36650953, 2023). "The expression of ADORA2A was present in tumors from both groups, but it was notably lower in the high NUSAP+ Glioma score group relative to the low scoring group." (PMID 39975552, 2025).
Obesity (16 papers, 2017 to 2025). Accumulation of substantial excess body fat. "In conclusion, the dysfunction of adenosine-A2AR mediated by ADORA2A mutations may be a common cause of obesity and COVID-19 due to disrupted adenosine function." (PMID 38352709, 2024). "ADORA2A-mediated signaling results in the breakdown of the blood–brain barrier, which is induced by obesity." (PMID 35669396, 2022). "Increased mitophagy together with stable mitochondrial biogenesis attenuate obesity-induced OA upon adenosine A2A receptor treatment." (PMID 32882839, 2020). "While the APOE4 mice do not demonstrate increased gliosis at this stage of developing obesity, there could be stronger inflammation and neuronal damage if increased Adora2a expression persisted." (PMID 34537055, 2021).
Cerebral ischemia (14 papers, 2014 to 2025). Restriction of arterial blood supply to the brain associated with insufficient oxygenation to support the metabolic requirements of the tissue. "Another study using Adora2a-/- mice showed that inactivation of endothelial ADORA2A protected mice from cerebral ischemia-induced brain injury and improved post-stroke outcomes through anti-inflammatory effects and blockade of NLRP3 inflammasome activity." (PMID 36118760, 2022). "Induction of cerebral ischemia decreased the levels of cAMP concentration and adenosine A2A receptor expression (P < 0.05), and treatment with PDRN improved the levels of cAMP concentration and adenosine A2A receptor expression (P < 0.05)." (PMID 33735236, 2021). "Co-administration of PDRN and adenosine A2A receptor antagonist DMPX attenuated the therapeutic effect of PDRN in cerebral ischemia." (PMID 33735236, 2021). "When considering use of adenosine A2A receptor active drugs to protect against brain ischemia, attention should be given to administration time after injury and to the dose used." (PMID 25165414, 2014). "The increase in neurotrophic factor expression by adenosine A2A receptor stimulation may contribute to restore neurological functions and cerebral damage after brain ischemia." (PMID 25165414, 2014). "The co-administration of PDRN and DMPX failed to increase the levels of cAMP concentration and adenosine A2A receptor expression observed with PDRN in cerebral ischemia." (PMID 33735236, 2021).
Stroke (14 papers, 2014 to 2025). Sudden impairment of blood flow to a part of the brain due to occlusion or rupture of an artery to the brain. "Similar to Pde10a, Adora2a and Drd2 belong to the cAMP signaling pathway, which is known to regulate synaptic plasticity and be involved in functional recovery after stroke." (PMID 36833381, 2023). "The QKO mice exhibited some eye inflammation and dermatitis, like Adora2a−/− mice (Dorian McGavern, National Institute of Neurological Disorders and Stroke, personal communication)." (PMID 30822301, 2019). "Focus on inflammatory responses provides for adenosine A2A receptor agonists a wide therapeutic time-window of hours and even days after stroke." (PMID 25165414, 2014). "In addition, ADORA2A and DRD2 receptors have been associated with the suppression of neuroinflammation through the modulation of microglia after stroke." (PMID 36833381, 2023).
autoimmune disease (13 papers, 2011 to 2025). A disorder resulting from loss of function or tissue destruction of an organ or multiple organs, arising from humoral or cellular immune responses of the individual to their own tissue constituents. "The adenosine A2A receptor and its activation may have a role in treating other Treg dysfunction-mediated autoimmune diseases." (PMID 29270168, 2017). "However, the function of adenosine A2A receptor in the development and control of autoimmune diseases remains unclear." (PMID 29270168, 2017). "Moreover, ADORA2A indirectly modulates pathways such as phosphatidylinositol 3-kinase/protein kinase B (PI3K/AKT), which play crucial roles in autoimmune diseases and biliary disorders." (PMID 41142241, 2025). "In summary, our study demonstrates that adenosine A2A receptor deletion does not inhibit the development of autoimmune disease in the SF mouse." (PMID 29270168, 2017).
gastric cancer (13 papers, 2020 to 2025). A primary or metastatic malignant neoplasm involving the stomach. "It is demonstrated through these data that adenosine signaling through Adora2a is important in the pathogenesis of gastric cancer." (PMID 41346607, 2025). "In gastric cancer models, high expression of the adenosine A2a receptor (A2aR) enhances AKT and mTOR activity, accelerating DSB repair and improving tumor cell survival." (PMID 40725100, 2025). "In gastric cancer cells, miR-214-3p was shown to induce the Warburg effect by directly targeting genes for the adenosine A2A receptor (A2AR) and PR/SET domain 16 (PRDM16) and promoting migration and cell proliferation." (PMID 36768818, 2023). "Its upregulation in gastric cancer exceeds that of Adora2a and correlates with invasive phenotypes." (PMID 41346607, 2025). "There is a great need to better understand the role of CD73 and Adora2b in gastric cancer, whether blocking adenosine signaling through inhibition of CD73 and/or Adora2a/Adora2b antagonism improves the potential for anti-tumor immunity in gastric cancer." (PMID 41346607, 2025).
cognitive decline (12 papers, 2017 to 2025). "It has been found, however, that the variants of ADORA2A were associated with the degeneration of hippocampal gray matter in both schizophrenic patients and aging populations with cognitive decline." (PMID 35187019, 2021).
diabetes (11 papers, 2012 to 2023). "We previously showed that the adenosine A2A receptor is downregulated in experimental diabetes associated with spontaneous hypertension." (PMID 33238361, 2020). "Interestingly, this difference was observed in the same renal structures where we previously demonstrated a decrease in the expression of the adenosine A2A receptor associated with the induction of diabetes in SHR when compared with normoglycemic SHR." (PMID 33238361, 2020). "The adenosine A2A receptor mRNA and protein levels are increased in the renal cortex of diabetic rats, and diabetes has also been associated with increased glomerular expression of adenosine A2B receptors and increased cortical levels of the adenosine A3 receptor protein." (PMID 31150459, 2019). "Taken together, the ADORA2A/mairin combination could be a promising therapeutic strategy for diabetes in future." (PMID 35669396, 2022). "In this line, it has been previously demonstrated that mice lacking ADORA2A (A2AR KO) are highly susceptible to MLDS-induced diabetes, with the presence of hyperproliferative T cells." (PMID 29769837, 2018). "In contrast, overexpression of CD39 protected mice from diabetes, through the production of ADO and activation of ADORA2A and ADORA2B." (PMID 29769837, 2018).
liver fibrosis (11 papers, 2008 to 2024). "In response to adenosine, HSC up-regulate collagen and transforming growth factor, and inhibition of the adenosine A2A receptor signaling decreases liver fibrosis in vivo." (PMID 24782773, 2014). "This is consistent with recent reports showing that antagonism of adenosine A2a receptor prevents and reverses liver fibrosis and antagonism of adenosine A1 receptor reduces mortality of cirrhotic rats." (PMID 24651845, 2014). "Evidence suggests that adenosine aggravates liver fibrosis via the adenosine A2A receptor (A2AR)." (PMID 24682220, 2014). "Overstimulation of ADORA2A is probably a pathogenetic factor in scleroderma and hepatic fibrosis." (PMID 18385786, 2008). "The adenosine A2A receptor (A2A) is known to be present on HSC, and its activation results in liver fibrosis." (PMID 24782773, 2014).
neuroblastoma (11 papers, 2014 to 2025). Neuroblastoma (NB) is the most common solid, extracranial childhood tumor. "In human and murine neuroblastoma cell lines, ADORA2A showed the highest expression in the ADORA family, which is in line with findings that this adenosine receptor is highly expressed in brain and neuroblastoma cells." (PMID 35216410, 2022).
psychosis (11 papers, 2010 to 2023). "We therefore hypothesized that variations in the A2A adenosine receptor (ADORA2A) gene modify genetic susceptibility to METH dependence/psychosis." (PMID 20799992, 2010). "Association analyses between these SNPs in the ADORA2A gene and METH dependence/psychosis were performed using DNA samples from 171 METH dependent/psychotic subjects and 229 control subjects." (PMID 20799992, 2010). "Further investigations of the role of the ADORA2A gene in the development of METH dependence/psychosis are warranted." (PMID 20799992, 2010). "This is the first report of an association analysis between ADORA2A gene polymorphisms and METH dependence/psychosis." (PMID 20799992, 2010). "In addition, DRD2 represents an interesting pharmacological target for the treatment of psychosis and ADORA2A has been suggested as a target for the treatment of psychiatric diseases." (PMID 25340473, 2014). "Our results suggest that the ADORA2A gene could be a vulnerability factor for METH dependence/psychosis, especially in females and/or in patients using only METH." (PMID 20799992, 2010).
Arthritis (10 papers, 2015 to 2024). Inflammation of a joint. "Adenosine is recognised to mediate anti-inflammatory effects via the adenosine A2a receptor (A2aR), as shown in experimental models of arthritis." (PMID 26920550, 2016).
asthma (9 papers, 2017 to 2025). "Although ADORA2A agonists have shown promising results in animal models of asthma and COPD, there has been less success in human clinical trials, largely due to limited efficacy." (PMID 35386996, 2021). "ADORA2A is targeted by multiple drugs such as oxtriphylline for treatment of the symptoms of asthma, bronchitis, COPD, and emphysema." (PMID 28245581, 2017). "Similarly, using whole blood samples, polymorphisms of ADORA3 have been identified in patients with aspirin-induced urticaria, of ADORA1 and ADORA2A in aspirin-induced asthma, both in Korean population; ADA polymorphism have been observed in asthma patients from a Chinese Han population." (PMID 34068999, 2021). "The adenosine receptors (ADORA1, ADORA2A, ADORA2B, and ADORA3) have a promising therapeutic role in asthma and chronic obstructive pulmonary disease (COPD)." (PMID 35052792, 2022). "Conversely, ADORA2A agonists are considered to be potential treatments for asthma and COPD, since ADORA2A is important for controlling the balance between the immune cells in allergic asthma by simultaneously increasing immunosuppressive Treg cells and decreasing pro-inflammatory Th17 cells in mice." (PMID 35386996, 2021).
colorectal cancer (9 papers, 2019 to 2025). A primary or metastatic malignant neoplasm that affects the colon or rectum. "Subsequently, we verified ADORA2A expression in colorectal cancer cell lines with stable SETDB1 knockdown by qRT-PCR and western blotting, respectively." (PMID 37945707, 2023). "And we further explored ADORA2A expression in colorectal cancer cell lines." (PMID 37945707, 2023). "ADORA2A overexpression encourages the biologically malignant nature of colorectal cancer." (PMID 37945707, 2023).